CD38 (CD38 molecule)
Diseases named in the same sentence as CD38 in open-access papers (continued):
Sharing a sentence is not in itself a finding about the gene and the disease.
melanoma (continued). "We detected upregulated LGALS9 (p = 0.029) and CD38 (p = 0.14) in the sEV cargoes in the blood plasma sEVs of melanoma patients than in healthy donors." (PMID 41271007, 2025). "In a melanoma tumor model, CD38 was similarly found to be highly expressed in exhausted CD8+ T cells and showed a correlation with ICB resistance." (PMID 39519411, 2024). "To begin to delineate the phenotypic and functional traits associated with CD38-expressing CD8+ T cells and their involvement in anti-PD1 resistance, we employed the highly aggressive B16-F10 melanoma tumor model, which has shown resistance to immunotherapy." (PMID 38451948, 2024). "We also found genes that are associated with melanoma metastases formation (CCL8, CD38) and melanoma cell migration and invasion (KRT5)." (PMID 38671536, 2024). "In multiple TCGA cohorts, including ovarian cancer, sarcomas and melanoma, CD38+ CD19+ correlated with better OS, suggesting a prognostic effect." (PMID 37365284, 2023). "Studies have found that the high CD38 in melanoma patients can be used as biomarkers for anti-PD-1 resistance." (PMID 34805163, 2021). "In this regard, T cell proliferation was restored by using kuromanin, a specific CD38 inhibitor, providing indirect evidence for the central role played by CD38 in melanoma-mediated immunosuppression." (PMID 33936090, 2021). "An effect of CD38 inhibition is the reduction of adenosine in the melanoma TME that results in the inhibition of antitumor responses." (PMID 33727923, 2021). "This suggests that, at least in part, the effect of CD38 inhibition on melanoma is due to the reduction of NAADP production." (PMID 31861847, 2019). "The murine evidence was supported with human lung tumor data, in which ~25% of lung tumor cells expressed CD38 in strong correlation to the degree of T cell infiltration, while in melanoma patient samples, CD38 is upregulated after treatment with anti-PD-1." (PMID 31878283, 2019). "As compared to healthy donors, circulating CD56bright NK cells of melanoma patients showed elevated expression of CD11a, CD38 and CD95, as measured directly ex vivo." (PMID 30872676, 2019). "The inhibition of CD38 appears to suppress melanoma progression through multiple mechanisms and pathways, making CD38 a potent therapeutic target for the treatment of melanoma." (PMID 31861847, 2019). "Collectively, our results suggest that targeting CD38 in the melanoma TME provides a new therapeutic approach for melanoma treatment." (PMID 30159123, 2018). "ii) Treating B16F10 melanoma-bearing WT mice with a CD38 inhibitor restrained primary melanoma growth when applied together with tumor cells or after tumor occurrence." (PMID 30159123, 2018). "In this respect it was shown that primary human melanoma cell lines suppress in vitro T cell proliferation through the CD38, CD203a and CD73 pathway." (PMID 30159123, 2018). "To test if the inhibitory effect of targeting CD38 on melanoma outgrowth is general, we utilized additional syngeneic mouse melanoma model, namely the RMS melanoma cells." (PMID 30159123, 2018). "The results show that K-rhein significantly attenuated the subsequent tumor growth and prolonged survival of the melanoma-bearing mice (median survival of Cd38‒/‒ mice was 23 days versus 21 days of WT mice)." (PMID 30159123, 2018). "Using mouse melanoma models we demonstrate that targeting CD38 in the melanoma TME inhibited outgrowth of primary melanoma and reduced the occurrence of spontaneous pulmonary and brain metastases." (PMID 30159123, 2018). "Since K-rhein inhibited B16F10 melanoma outgrowth in a CD38-dependent manner, it is feasible that the CD38 enzyme activity in the TME support melanoma growth." (PMID 30159123, 2018). "The novelty of the present study is the finding that targeting CD38 can also inhibit extracranial tumor (melanoma) outgrowth by a mechanism that involves reduction in the amount of CAFs and blood vessels." (PMID 30159123, 2018).
melanoma (continued). "CD38 inhibitors have been shown to be effective against melanoma in different mouse models." (PMID 36605482, 2023). "Therefore, blocking the CD38-mediated adenosine pathway seems to reduce the immunosuppression in melanoma." (PMID 35251964, 2022). "Evidence is provided for the role of new markers such as CD38 for treatment resistance in melanoma, which might have direct therapeutic consequences." (PMID 34360781, 2021). "In melanoma anti-PD-1 and anti-CTLA-4 based immunotherapies improve survival significantly in advanced cases while targeting CD38 in melanoma TME could provide synergistic effects." (PMID 33727923, 2021). "CD38 could increase fibroblastic migration towards tumor cells and enhance melanoma invasive behavior." (PMID 34211854, 2021). "Hence, CD38 has been proposed as a prognostic marker in some pathologies and several therapeutic anti-CD38 monoclonal antibodies are currently being developed for the treatment of malignancies such as melanoma." (PMID 33329591, 2020). "Chen and colleagues have significantly contributed to expanding the knowledge in this field: they have detected up-regulation of CD38 in murine models of lung cancer and melanoma chronically exposed to PD-1/PDL-1 inhibitors, independent of tumor histological type." (PMID 32225002, 2020). "Thus, blocking the CD38-mediated adenosinergic pathway appears to reduce immunosuppression in melanoma." (PMID 31861847, 2019). "Thus, loss of CD38 also attenuates the occurrence (represented by number metastatic foci) and burden (represented by mCherry mRNA levels) of spontaneous RMS melanoma metastases." (PMID 30159123, 2018). "Meta-analysis of associations between pretreatment melanoma and NMSC tumors was significant for the combined ASA and cell cycle scores (P = 0.0072 and P = 0.0036, respectively) and for many cGEPs (for example, CellCycle-Late-S, exhaustion, ICOS/CD38; P < 0.05 all)." (PMID 40903640, 2025). "al., focused on the effect of NAADP on the tumor, but not the TME cells, a possible mechanism of loss of CD38 on melanoma could be a reduction in production of NAADP by the TME cells." (PMID 30159123, 2018). "Collectively, our results suggest that targeting CD38 in the melanoma TME may be a beneficial approach to treat melanoma both as a neoadjuvant treatment, to reduce tumor growth before resection of primary tumor, as well as for inhibiting the occurrence of metastasis." (PMID 30159123, 2018). "High levels of CD38, LGALS9, and TNC were found in the sinuses of the lymph node, supporting potential immunological targets for the PMN in melanoma." (PMID 41271007, 2025). "CD38 participates in adenosine generation via the CD203a/CD73 pathway, in selected tumors such as non-small-cell lung cancer (NSCLC) and melanoma, where the increased CD38 expression contributes to increased adenosine production and immunosuppressive effects." (PMID 39996780, 2025). "Anti-PD-1 enhanced T-cell immunity during SARS-Cov-2 infection in patients with melanoma, increased expansion of TEM, and induced the appearance of activated CD38+HLA-DR+ TEM cells of the same phenotype as in our study." (PMID 38032111, 2023). "Consistently, high levels of CD38 have been found in many tumors, indicating therapeutic approaches, such as the use of CD38−/− model mice and CD38 inhibitors to inhibit the progression of glioma, lung adenocarcinoma and the outgrowth of primary melanoma." (PMID 36078044, 2022). "Primary melanoma cell lines can inhibit the proliferation of CD4+ and CD8+ T cells through adenosine-dependent mechanisms; however, it has been found that the use of CD38 inhibitors can reverse this effect and restore T cell proliferation." (PMID 35251964, 2022). "Targeting CD38 mediated NAADP synthesis, which is responsible for neoangiogenesis and Ca++ signaling, with Ned-19, an NAADP inhibitor, constrained melanoma growth, vascularization, and metastasis." (PMID 33727923, 2021).
melanoma (continued). "We used seven-color multiplex immunostaining (CD20, CD19, CD5, CD27, CD38, CD138, and DAPI) to approximate six different TAB subpopulations in whole tissue sections of melanoma metastases from 41 different patients." (PMID 31519915, 2019). "The patients’ CD56bright NK cells showed upregulation of CD11a, CD38 and CD95 as compared to healthy controls, pointing to an activated phenotype as well as a possible immune regulatory role in melanoma patients." (PMID 30872676, 2019). "This review evaluates and integrates current data on the roles of CD38 in several cancer types including HCC, NSCLC, melanoma, pancreatic cancer, glioma and breast cancer." (PMID 31861847, 2019). "CAFs are known to play a supportive role in the progression of various solid tumors including melanoma, we therefore assessed the level of CAFs (identified by the marker α-SMA) in tumors grown in WT and Cd38‒/‒ mice." (PMID 30159123, 2018). "Melanoma cells inhibited T cell proliferation through an ADO-dependent mechanism, since such inhibition was reverted using CD38/CD73 specific inhibitors." (PMID 26329660, 2015). "This study demonstrates that primary melanoma cells are equipped with both the canonical (CD39/CD73) and the alternative (CD38/CD157/CD203a(PC-1)/CD73) ectoenzymatic pathways for producing ADO at the interface between tumor and host." (PMID 26329660, 2015). "•Melanoma-negative sentinel lymph node carries more contents of the sEV cargoes, CD38, LGALS9 (galectin-9), and TNC (tenascin-C), in the lymphatic sinuses compared with control lymph nodes." (PMID 41271007, 2025). "The proteins CD38, LGALS9, and TNC were selected for evaluation to determine whether lymphatic sinuses in melanoma patients exhibit elevated levels of these proteins compared with control LN sinuses." (PMID 41271007, 2025). "Furthermore, the upregulation of key melanoma-specific cargoes: LGALS9 (p = 0.029), CD3D (p = 0.097), and CD38 (p = 0.14) in the blood plasma sEVs of melanoma patients was noted in contrast to healthy donors." (PMID 41271007, 2025). "Distinct immune signatures, such as CD8+PD-1+ T cells, CD8+ effector memory (CD8+CD45RA−CD45RO+CCR7−) T cells, activated CD4+ T cells (CD4+CD38+HLA-DR+), and NK cells (CD16+CD56+CD38+HLA-DR+) showed the treatment response and immune-related adverse events in melanoma patients in ICI therapy." (PMID 36569825, 2022). "In patient samples, the fraction of PD1+CD38+CD8+ T cells was higher in cells extracted from melanoma lesions in non-responders compared to responders." (PMID 34360781, 2021). "In tumors, CD73 and CD39 were found to both be overexpressed and functionally active in producing adenosine in ovarian cancer cells, and melanoma cells expressed the enzymes for both the canonical (CD39/CD73) and alternative (CD38/CD203a) pathways for adenosine production." (PMID 31878283, 2019). "The sequential activity of CD38, CD203a, and CD73 results in the production of adenosine, and extracellular adenosine is known to be a powerful inhibitor of the anti-tumor immune response in melanoma." (PMID 31861847, 2019). "Primary melanoma cell lines have been found to suppress the proliferation of CD4+ and CD8+ T cells through an adenosine-dependent mechanism, but the use of CD38 and CD73 inhibitors have been found to reverse this effect, resulting in the restoration of T cell proliferation." (PMID 31861847, 2019). "Collectively, these results show that targeting CD38 by preventing its expression in the TME, or by inhibiting its enzymatic activity at the time of tumor cell implantation or after tumor establishment, attenuates B16F10 melanoma outgrowth." (PMID 30159123, 2018). "Kaplan-Meier analysis revealed that K-rhein also significantly prolonged survival of melanoma-bearing WT, but not Cd38‒/‒ mice." (PMID 30159123, 2018).
melanoma (continued). "ACT using Pmel or CD38 knockout Pmel (Pmel-CD38−/−) T cells either alone or in combination with anti-PD1 therapy delayed tumor progression in mice bearing B16-F10 mouse melanoma tumor as compared to mice without ACT (control)." (PMID 38451948, 2024). "The low levels of ADO production by melanoma cells observed after providing NAD+ as substrate may indicate that enzymatic function either of CD38 or CD203a/PC-1, which converts ADPR produced from NAD+ by CD38 to AMP, is inefficient." (PMID 26329660, 2015). "In these tumor cells, CD38 and CD73 expression was constantly detected, whereas CD39 and CD203a were highly expressed in some primary melanoma cells, and low to absent in the others." (PMID 33936090, 2021). "Activation and cell cycle cGEPs were elevated in pretreatment nonresponders of melanoma and NMSC (meta-analysis P < 0.05 for CellCycle-G2M, CellCycle-Late-S, TIMD4/TIM3, exhaustion, ICOS/CD38, OX40/EBI3 and HLA) and in the combined CRC cohort (P < 0.05 for all)." (PMID 40903640, 2025).
Obesity (45 papers, 2008 to 2026). Accumulation of substantial excess body fat. "CD38 is heavily involved in diet-induced obesity and is the protein that shows the most consistent association with cardiometabolic and brain health." (PMID 40943443, 2025). "CD38 knockout mice or CD38 inhibitor-treated mice exhibited increased metabolic rates and lower risk of metabolic syndromes, such as obesity." (PMID 40529366, 2025). "CD38 dysfunction is associated with various pathophysiological processes, including aging, metabolic disorders (such as obesity/diabetes), cardiovascular disease, and chronic inflammation." (PMID 41001131, 2025). "Ablation of SIRT3 in CD38-deficient mice eliminates the protective role of CD38 inhibition in HFD-induced obesity." (PMID 36794157, 2023). "The study demonstrated that CD38-deficient mice were substantially more resistant to the obesity-inducing effects of HFD, and that WT mice fed HFD had significantly higher CD38 expression." (PMID 36794157, 2023). "We previously demonstrated that CD38 deficiency protected against inflammation, obesity, cardiac hypertrophy, ischemia/reperfusion injury and cardiomyocyte senescence 11-14." (PMID 34803499, 2021). "Previously, CD38 has been implicated to help regulate multiple chronic conditions/diseases, such as aging, obesity, and diabetes, through degradation of NAD." (PMID 32363189, 2020). "Mice deficient in CD38 are protected against the high-fat diet-induced obesity due to boosted metabolic rate in part via a NAD-dependent stimulation of SIRT-PGC1alpha axis." (PMID 33414897, 2020). "To explore the molecular mechanisms underlying CD38 deficiency‐mediated inhibition of obesity, we detected the protein expression levels of Sirt1 and the target gene PPARγ which was known to promote adipocyte differentiation." (PMID 28816006, 2018). "In the present study, we also confirmed that CD38 deficient mice were significantly resistant to HFD‐induced obesity." (PMID 28816006, 2018). "The loss of CD38 activity either by genetic deletion or through the use of a small molecule inhibitor can protect mice from diet-induced obesity and insulin resistance." (PMID 26287487, 2015). "While previous NAD+ restoration strategies have primarily targeted biosynthetic pathways, our findings demonstrate that co-targeting degradation (e.g., CD38 inhibition) yields comparable benefits, thereby expanding the therapeutic landscape for age- and obesity-associated metabolic disorders." (PMID 41397559, 2026). "Our previous study reported that CD38 deficiency alleviated HFD-induced obesity." (PMID 37958991, 2023). "NAD+ levels are maintained in CD38-deficient mice during aging and obesity stress." (PMID 36986224, 2023). "CD38 expression increases during aging and CD38 knockout models exhibit heightened NAD+ levels and protection against obesity, metabolic disorders, and cancer progression, illuminating CD38′s role in increasing the risk of developing age-related metabolic diseases." (PMID 36678315, 2023). "Therefore, based on the results of this study, we concluded that CD38 deficiency‐mediated activation of Sirt1 signalling pathway plays a critical role in the development of obesity." (PMID 28816006, 2018). "However, whether the protection of CD38 deficient mice on the obesity induced by HFD is involved in inhibitions of adipogenesis or/and lipogenesis is still unknown." (PMID 28816006, 2018). "Previous studies have shown that CD38 knockout mice have higher NAD+ levels that protect against obesity and metabolic syndrome." (PMID 40332514, 2025). "Inhibition of CD38 in obesity models led to an enhanced metabolic profile, increased NAD+ levels, and decreased protein acetylation, possibly due to enhanced SIRT1 activity due to higher NAD+ availability." (PMID 36678315, 2023). "CD38 mRNA in adipose tissue is up-regulated not only in animal models of diet-induced obesity but also in some genetic models." (PMID 37761000, 2023).